OPRD1 (opioid receptor delta 1)
Description:
G protein-coupled receptor that functions as a receptor for endogenous enkephalins and for a subset of other opioids. Ligand binding causes a conformation change that triggers signaling via guanine nucleotide-binding proteins (G proteins) and modulates the activity of down-stream effectors, such as adenylate cyclase. Signaling leads to the inhibition of adenylate cyclase activity. Inhibits neurotransmitter release by reducing calcium ion currents and increasing potassium ion conductance. Plays a role in the perception of pain and in opiate-mediated analgesia. Plays a role in developing analgesic tolerance to morphine.
Synonyms: OPRD; DOP; DOR; DOR1
Tractability: Small molecule: an approved drug acts on it; a structure with a bound ligand is known; a high-quality ligand is known; it belongs to a druggable protein family. Antibody: UniProt places it where antibodies can reach, with high confidence; its Gene Ontology location is reachable by antibodies, with high confidence; UniProt predicts a signal peptide or a membrane-spanning region. PROTAC: UniProt records ubiquitination sites on it; a small molecule that binds it is known.
Target class: Short peptide receptor (family A GPCR); Family A G protein-coupled receptor; Peptide receptor (family A GPCR); Opioid receptor; Membrane receptor
Chemical probes: ADL-5747 (high quality), CHEMBL246003, CHEMBL294616, CHEMBL3596369
Safety:
Unwanted effects reported when the protein is acted on. In parentheses: how it was acted on, where the effect was seen, and who reports it.
analgesia (Urban et al. (2012): activation, cardiovascular system, nervous system; Bowes et al. (2012): activation, cardiovascular system, central nervous system)
cardiovascular effects (Urban et al. (2012): activation, cardiovascular system, nervous system; Bowes et al. (2012): activation, cardiovascular system, central nervous system)
convulsion (Urban et al. (2012): activation, cardiovascular system, nervous system; Bowes et al. (2012): activation, cardiovascular system, central nervous system)
dysphoria (Bowes et al. (2012): activation, cardiovascular system, central nervous system; Urban et al. (2012): activation, cardiovascular system, nervous system)
increased blood pressure (Urban et al. (2012): inhibition, cardiovascular system, nervous system; Bowes et al. (2012): inhibition, cardiovascular system, central nervous system)
psychomimetic effects (Bowes et al. (2012): activation, cardiovascular system, central nervous system; Urban et al. (2012): activation, cardiovascular system, nervous system)
respiratory depression (Lynch et al. (2017): activation, acute dosing, central nervous system; Urban et al. (2012): activation, cardiovascular system, nervous system)
convulsions (activation, acute dosing; central nervous system; source: Lynch et al. (2017))
decreased body temperature (activation, acute dosing; central nervous system; source: Lynch et al. (2017))
decreased gastrointestinal transit (activation, acute dosing; central nervous system; source: Lynch et al. (2017))
decreased pain (activation, acute dosing; central nervous system; source: Lynch et al. (2017))
euphoria (activation, acute dosing; central nervous system; source: Lynch et al. (2017))
heart effects (activation; cardiovascular system, nervous system; source: Urban et al. (2012))
increased anxiety (inhibition, acute dosing; central nervous system; source: Lynch et al. (2017))
increased bloodflow to the gastrointestinal tract (inhibition; cardiovascular system, nervous system; source: Urban et al. (2012))
increased bloodflow to the heart (inhibition; cardiovascular system, nervous system; source: Urban et al. (2012))
increased bloodflow to the kidneys (inhibition; cardiovascular system, nervous system; source: Urban et al. (2012))
increased bloodflow to the skeletal muscle (inhibition; cardiovascular system, nervous system; source: Urban et al. (2012))
increased cardiac contractility (inhibition; cardiovascular system, central nervous system; source: Bowes et al. (2012))
increased cardiac output (inhibition; cardiovascular system, nervous system; source: Urban et al. (2012))
increased contractility (inhibition; cardiovascular system, nervous system; source: Urban et al. (2012))
increased locomotor activity (activation, acute dosing; central nervous system; source: Lynch et al. (2017))
increased pain (inhibition, acute dosing; central nervous system; source: Lynch et al. (2017))
seizure (activation; cardiovascular system, nervous system; source: Urban et al. (2012))
cocaine dependence (source: ClinPGx)
heroin dependence (source: ClinPGx)
sexual dysfunction or reproductive system disorders (source: ClinPGx)
Gene: Protein-coding gene on chromosome 1 (28,812,170 to 28,871,267, forward strand). Ensembl gene ENSG00000116329.
Subcellular location: Cell membrane
Pathways (Reactome):
Signal Transduction: G alpha (i) signalling events; Peptide ligand-binding receptors
Immune System: Interleukin-4 and Interleukin-13 signaling
Gene Ontology:
Molecular function: G protein-coupled enkephalin receptor activity; G protein-coupled opioid receptor activity; protein binding; neuropeptide binding; G protein-coupled peptide receptor activity; G protein-coupled receptor activity; receptor serine/threonine kinase binding
Biological process: cellular response to hypoxia; cellular response to toxic substance; G protein-coupled opioid receptor signaling pathway; G protein-coupled receptor signaling pathway; negative regulation of gene expression; negative regulation of protein-containing complex assembly; regulation of mitochondrial membrane potential; G protein-coupled receptor signaling pathway, coupled to cyclic nucleotide second messenger; immune response; neuropeptide signaling pathway; phospholipase C-activating G protein-coupled receptor signaling pathway; cellular response to growth factor stimulus; eating behavior; regulation of calcium ion transport; response to ethanol; response to nicotine
Cellular component: plasma membrane; neuron projection; axon terminus; dendrite membrane; membrane; neuronal dense core vesicle; postsynaptic density membrane; postsynaptic membrane; presynaptic membrane; spine apparatus; synaptic vesicle membrane; vesicle
Genetic constraint (gnomAD): Loss-of-function variants: 17 observed, 17.63 expected, observed/expected ratio (o/e) 0.96, 90% interval 0.66 to 1.45. The upper end of that interval is the gene's LOEUF score, 1.45, which puts it in group 5 of 6, group 1 being the genes least tolerant of losing a copy. Missense variants: 448 observed, 460.08 expected, observed/expected ratio (o/e) 0.97, 90% interval 0.9 to 1.05. Synonymous variants: 233 observed, 202.48 expected, observed/expected ratio (o/e) 1.15, 90% interval 1.03 to 1.28.
Homologues: Orthologues: chimpanzee OPRD1 (99% identical), dog OPRD1 (97% identical), rabbit OPRD1 (96% identical), pig OPRD1 (95% identical), guinea pig OPRD1 (95% identical), mouse Oprd1 (94% identical), rat Oprd1 (94% identical), tropical clawed frog oprd1 (72% identical), zebrafish oprd1a (69% identical), zebrafish oprd1b (68% identical), Caenorhabditis elegans trhr-1 (23% identical), Drosophila melanogaster Rh7 (21% identical). Paralogues in human: OPRM1 (59% identical), OPRK1 (57% identical), OPRL1 (51% identical), SSTR4 (38% identical), SSTR1 (38% identical), SSTR5 (36% identical), NPBWR2 (34% identical), SSTR2 (34% identical), SSTR3 (34% identical), NPBWR1 (33% identical), KISS1R (30% identical), PTGDR2 (26% identical), and 5 more.